SFRP1 (secreted frizzled related protein 1)
Diseases named in the same sentence as SFRP1 in open-access papers (continued):
Sharing a sentence is not in itself a finding about the gene and the disease.
tumor (continued). "Upon binding to the WNT protein, SFRP1 inhibits the ligand receptor binding and hence circumvents WNT signaling which therefore behaves both as oncogenic as well as a tumor suppressor signal depending on the context." (PMID 30647841, 2018). "However, emerging evidence suggests that sFRP1 may also promote tumour growth." (PMID 28169332, 2017). "SFRP2 and SFRP5 tumour-suppressive activity in eleven MPM lines was confirmed, and long-term asbestos exposure led to reduced expression of the SFRP1 and SFRP2 genes in the mesothelium (MeT-5A) via epigenetic alterations." (PMID 29386699, 2017). "The percentage of methylated reference (PMR) levels of SFRP1, SFRP2, PRKCB and WIF1 in 111 NSCLC tumor tissues and 111 paired adjacent tissues were quantified by SYBR green-based quantitative methylation-specific PCR (qMSP)." (PMID 28422739, 2017). "The meta-analysis of p14, p15, p73, APC, SOCS1, MGMT, SFRP1, PRDM2, DAPK1, RARβ, IGF2 and hMLH1 genes methylation was performed between HCC tumor tissues vs adjacent tissues and HCC tumor tissues vs normal tissues." (PMID 27835605, 2016). "This means that the SFRP1 expression is up-regulated in SHH tumors and down-regulated in WNT sample and matches the current knowledge that SFRP1 is a tumor suppressor gene responsible for Hedgehog signaling mediated regulation of the WNT signaling pathway." (PMID 25861969, 2015). "The present study revealed a significant increase in SFRP1, SHH and Gli1 expression in irradiated tumor cells." (PMID 25713298, 2015). "Re-expression of BNC1, CST6, and SFRP1 suppressed the growth of RCC cell lines, whereas RNAi knock-down of BNC1, SFRP1, and COL14A1 increased their growth, suggesting tumor suppressor activity." (PMID 28326264, 2015). "Here we demonstrated retained protein expression of well-known Wnt inhibitor, secreted frizzled-related protein 1 (SFRP1) in stromal myofibroblasts and decreasing epithelial expression from NAT tissues towards the tumor." (PMID 25405986, 2014). "We also found that the sequential treatment group induced re-expression or increased expression of the Wnt antagonist genes (SFRP1, HDPR1 and DKK3) in tumor cells of the subcutaneous AML mouse." (PMID 24923330, 2014). "A total of 219 CpG sites (185 hypermethylated and 34 hypomethylated) in 147 unique genes were significantly differentially methylated between tumor and tumor-adjacent gastric tissue (FDR = 0.001), with the top three CpG sites located in HOXA5, SFRP1 and CCNA1." (PMID 24674026, 2014). "DNA methylation at the promoter region of the MGMT, CDKN2A, SFRP1, TMEFF2, HS3ST2 (3OST2), RASSF1A and GATA4 genes was evaluated by quantitative methylation specific PCR in both tumor and corresponding normal appearing colorectal mucosa samples." (PMID 20098741, 2010). "Two antagonists of WNT receptor signaling, WIF1 and secreted frizzled-related protein 1 (SFRP1), were downregulated in both the tumor epithelium and the stroma." (PMID 19187537, 2009). "In conclusion, sFRP1-mediated blockade of WNT signaling impairs the in vitro migratory ability and the in vivo metastatic ability of MDA-MB-231 tumor cells." (PMID 19473496, 2009). "To date, four SFRP family genes (SFRP1, SFRP2, SFRP4 and SFRP5) and two DKK family genes (DKK1 and DKK3) have been identified as targets of epigenetic silencing in human tumours." (PMID 18283316, 2008). "Our results were consistent with those of the meta-analysis such that GSN, SPTBN1, SFRP1 and MAF were down-regulated in most tumor samples with respect to their matched non-tumor samples whereas COX6C, RAD21, GSPT1, NME1 and PTTG1 were up-regulated." (PMID 19116033, 2008). "Thus, to disrupt tumor ASA by modulating cWnt signaling at the Q–A transition, we cloned SFRP1 downstream of the TCF/Lef-promoter in T6 GBM (“Methods”)." (PMID 40770193, 2025).
tumor (continued). "Reintroducing SFRP1 stalls tumor growth in vivo and reprograms the tumor from an NSC-like into an astrocyte-like methylome, significantly improving the overall survival of tumor-bearing mice." (PMID 40770193, 2025). "In contrast, the present study showed that Sfrp1 did not affect tumor angiogenesis or vascular structure." (PMID 38625488, 2024). "Tumor growth was suppressed 23 d after transplantation in Sfrp1 KO mice, but no changes were observed in the structure of tumor vasculature." (PMID 38625488, 2024). "Analysis using WT and Sfrp1 KO tumor model mice suggested that Sfrp1 is involved in maintaining the stemness of CCs without affecting tumor vasculature." (PMID 38625488, 2024). "Due to absence of expression in various cancers, SFRP1 is classified as a tumor suppressor, acting through DNA methylation or miRNA transcriptional silencing." (PMID 38309281, 2023). "The density plots indicated that the expression trend of FMO2 and SFRP1 in the normal, tumor, and metastatic tissues were consistent, regardless of gene chip data and RNA-sequence data." (PMID 37963835, 2023). "Western blot analysis showed that the relative expression level of SFRP1 in the tumour samples was lower than that in the nontumor tissues, while the relative expression level of H2A.Z in the tumour tissues was higher than that in the nontumor tissues." (PMID 36368958, 2022). "Methylation of GREM1, GATA5, LAD1, NEFH, NEURL, and SFRP1 was associated with poor ccRCC-specific survival, independent of age, sex, tumor size, TNM stage or tumor grade." (PMID 33947447, 2021). "Among the genes under control of these dual modifications were known tumour-suppressor genes such as IGFBP7 (insulin-like growth factor binding protein 7) and SFRP1 (secreted frizzled-related protein 1), and callponin 3 (CNN3) associated with cytoskeleton maintenance." (PMID 34884658, 2021). "Since LEF-1 has been related to tumor progression to metastasis and this gene has been reported to be regulated for ERG, we measured it’s expression in VCaP cells after treatment with exogenous SFRP1." (PMID 32694934, 2020). "Moreover, combination treatment of vactosertib with nal-IRI/5-FU/LV induced well-known tumour suppressors ITM2A and SFRP1." (PMID 32076068, 2020). "Thus, a downregulation of SFRP1 in HCC cells resulted in stimulated WNT signaling activity and increased tumor cell growth." (PMID 32189106, 2020). "SFRP1 is an extracellular inhibitor of the WNT pathway and acts as a tumor suppressor." (PMID 31380278, 2019). "As a total of 307 sporadic postoperative CRC patients were followed up, we detected SFRP1, SFRP2, and WIF1 methylation obtained from tumor tissues and adjacent non-tumor tissues respectively on the basis of methylation-sensitive high resolution melting analysis." (PMID 31830937, 2019). "SFRP1, SFRP2, and WIF1 were frequently hypermethylated in CRC tumor tissues." (PMID 31830937, 2019). "Four genes (EPB41L2, HLA-DQB1, LTF and SFRP1) were consistently overexpressed in initial tumor samples of subsequent nonresponders across multiple PFS cutoff times." (PMID 31195594, 2019). "The promoter of SFRP1, SFRP2, and WIF1 were frequently hypermethylated in CRC tumor tissues." (PMID 31830937, 2019). "Out of these, SFRP1, PI15 and RELN were downregulated as the tumor progresses toward malignancy." (PMID 30647841, 2018). "SFRP1, SFRP2 and PRKCB methylation levels could discriminate NSCLC tissues from adjacent non-tumor samples." (PMID 28422739, 2017). "Moreover, our results indicate that while SFRP1 is lost in cancer cells via the process of DNA methylation, SFRP2 and 4 are likely derived from the tumour stroma, and thus tend to increase in tumours as compared to normal tissues." (PMID 28218291, 2017). "We therefore deduced that SFRP1 might be the link between Wnt and SHH signaling pathways during tumor repopulation." (PMID 25713298, 2015).
tumor (continued). "Our manuscript mainly discussed the average methylation rate of SFRPs (SFRP1, SFRP2, SFRP4, and SFRP5) promoters are significantly high in tumor tissue samples and the average CpG island methylation rate among different pathological levels of cutaneous SCC between these genes are different." (PMID 26394929, 2015). "Given that BDNF is induced by forced SFRP1 re-expression in both luminal-like SKBR3 and basal-like BT20 tumor cells, we hypothesized a putative tumor suppressive role of BDNF." (PMID 25036590, 2014). "An influence of SFRP1 expression on the regulation of the BMP- and Smoothened signaling pathways could be concordantly demonstrated in both tumor models, luminal-like SKBR3 and basal-like BT20." (PMID 25036590, 2014). "In the luminal-like SKBR3 tumor model the SFRP1 expression had an influence on the regulation of the non-canonical Wnt signaling pathway (p<0.01)." (PMID 25036590, 2014). "Tumor samples from 155 patients with stages IIIB to IV NSCLC who received EGFR-TKI therapy were analyzed for DNA methylation status of Wnt antagonist genes, including SFRP1, SFRP2, SFRP5, DKK3, WIF1, and APC, using methylation specific PCR (MSP) method." (PMID 23009178, 2012). "To further examine the relationship between the methylation profile with patient characteristics and tumor markers, we focused on the 4 genes (RASSF1A, RARβ2, CDH13 and SFRP1) that showed the highest relative changes in tissue methylation status across the 65 tissue pairs." (PMID 22701537, 2012). "In summary, the results suggest that sFRP1 downregulation of WNT signaling has a strong effect on tumor cell proliferation, but not on survival." (PMID 19473496, 2009). "Their findings suggested that SFRP1, SEZ6L, CXX1, KIAA0786, S100A10 and TIMP2 might influence tumor development and progression." (PMID 19424480, 2008). "Wnt signaling pathway proteins, particularly SFRP1 and SFRP5, are crucial as their reduced levels due to promoter methylation lead to cytoplasmic and nuclear accumulation of β-catenin, facilitating tumor progression; thereby, these proteins may serve as biomarkers for malignant progression." (PMID 40565504, 2025). "Nim-NPs inhibit Wnt/β-catenin signaling by downregulating DNA methyltransferases, thus epigenetically restoring the expression of the secreted frizzled-related protein 1 (SFRP1) and resulting in tumor growth and metastasis formation inhibition without systemic toxicity." (PMID 39065798, 2024). "Moreover, the upregulation of miR26a could restore Enz sensitivity in vitro and in vivo, synergistically suppressing tumor growth, bone metastasis, and secondary metastasis by regulating the EZH2/SFRP1/WNT5A axis." (PMID 38566211, 2024). "Interestingly, some genes were already known to have a biological role in tumourigenesis, either as tumour suppressors (such as TUSC3) or elements of critical importance within tumour growth pathways (i.e., SFRP1 and FZD6, belonging to the Wnt signalling pathway)." (PMID 35327445, 2022). "Secreted frizzled-related protein 1 (SFRP1), a member of the SFRP family that contains a cysteine-rich domain, acts as a soluble modulator of Wnt signaling by directly interacting with Wnt, and plays a role in regulating the growth and differentiation of specific tumor cells." (PMID 36457747, 2022). "However, in SFRP1-null mice, no increases in the incidence of spontaneous tumor growth were observed." (PMID 34830873, 2021). "We also discovered several genes from the Wnt pathway with hypermethylation in EBVaGCs relative to LDs/normal tissues, including DKK3 (P = 0.0022), SFRP1 (P = 0.0034), and SFRP2 (P = 0.0005), and these genes have been reported to be frequently methylated and to function as tumor suppressors in NPCs." (PMID 34493320, 2021). "Moreover, ectopic sFRP1 expression in MDA-MB-231 cells has a strong negative impact on tumor outgrowth and blocked lung metastases." (PMID 19473496, 2009).
tumor (continued). "This is the first study to evaluate the concentrations of SFRP1, SFRP2, and SFRP5 in tumour and non-tumour (NT) samples from patients with primary NSCLC, including adenocarcinoma, squamous cell carcinoma, and large cell carcinoma." (PMID 37999144, 2023). "The aim of this study was to evaluate the concentrations of SFRP1, SFRP2, and SFRP5 proteins in tumour and non-tumour (NT) samples obtained from 65 patients with primary NSCLC." (PMID 37999144, 2023). "The expression among tumor stages varied significantly for SFRP2, SFRP3, and SFRP4, whereas the mRNA expressions of SFRP1 and SFRP5 were not markedly different." (PMID 34205081, 2021). "We had detected the methylation of SFRP1, SFRP2, and WIF1 for 187 adjacent non-tumor tissue specimens and 307 primary tumor tissue specimens." (PMID 31830937, 2019). "By contrast, levels of SFRP1 and SFRP2 methylation were consistently elevated in lesions throughout the entire bowel, indicating that those genes are methylated, irrespective of tumor location or the molecular subtype of the tumor." (PMID 27145369, 2016). "Third, SFRP1, but not SFRP2, is a potent angiogenic factor independent of Wnt signalling, suggesting its upregulation enhances tumor vascularisation." (PMID 22384081, 2012). "Tumor cells treated with RG108 at a low concentration resulted in a significant DNA demethylation and TSGs reactivation (p16, SFRP1, secreted frizzled related protein-1, and TIMP-3) without detectable toxicity." (PMID 20119531, 2009). "The resulting data showed that the transcriptional expression of SFRP1 was significantly reduced in HCC (p < 0.001) by comparing between tumor and non-cancerous liver groups." (PMID 17626620, 2007). "In the absence of Sfrp1 in the tumor environment, CSC growth increases in the early stages of tumor growth but decreases in the late stages, which may attenuate tumor progression." (PMID 38625488, 2024). "However, the levels of SFRP1 and SFRP5 were not significantly different between tumour and NT samples (p > 0.05)." (PMID 37999144, 2023). "As both SFRP1 and CREB3L1 could inhibit tumor proliferation, reduced CREB3L1 expression could not inhibit CCA proliferation, we excluded CREB3L1 and STK11 from our analysis." (PMID 27385214, 2016).
cancer (172 papers, 2004 to 2026). A tumor composed of atypical neoplastic, often pleomorphic cells that invade other tissues. "SFRP1 is a mature inhibitor of the Wnt signaling pathway, and its polymorphisms are associated with risks of inflammation, infection and cancer." (PMID 39617900, 2024). "Despite the limited involvement of SFRP1 in cancer clinical trials, research evidence has shown the potential of SFRP1 as a diagnostic and pharmacogenetics marker, and this has led to several patents being applied or granted." (PMID 32074995, 2020). "A systematic review and meta-analysis of the SFRP family also revealed that SFRP1 hypermethylation was significantly associated with cancer risk." (PMID 32074995, 2020). "In androgen-dependent prostate cancer, loss of SFRP1 undergoes different pathways other than Wnt and Hh signaling to drive cancer cell proliferation." (PMID 32074995, 2020). "This idea, however, needs to be addressed with care because of cancer enhancement potentials resulting from a systemic loss of SFRP1 activity, as well as an upregulation of ADAM10 activity." (PMID 32098349, 2020). "Prolonged inhibition of SFRP1 would therefore increase the risk for cancer, particularly in the aging brain in the context of late-onset AD." (PMID 32098349, 2020). "Following these initial reports, others went on to show similar trends and to tie the effects of SFRP1 loss to increased Wnt-related signalling in a variety of other cancers." (PMID 28218291, 2017). "We found that SFRP1 is the only family member whose expression is consistently decreased in primary cancer samples as compared to associated normal tissues." (PMID 28218291, 2017). "SFRP1 is involved in regulating apoptosis through Wnt signaling pathway and down-regulation or loss of SFRP1 has been shown to provide poor prognosis for cancer patients." (PMID 26497558, 2015). "Silencing of SFRP1 was observed in a wide range of malignancies, indicating that loss of SFRP1 is likely to be a common mechanism to activate the Wnt signaling pathway in human cancers." (PMID 25719802, 2015). "Epigenetic silencing of SFRP1 gene occurs in premalignant tissues associated with chronic inflammation or in human cancer." (PMID 26198328, 2015). "Genetic studies have shown that gene variants in SFRP1 are associated with inflammation and cancer risk." (PMID 24695522, 2014). "Altered SFRP1 expression has been reported to be associated with cell apoptosis in various conditions, including cancer, periodontitis, and bone disease." (PMID 23441124, 2013). "Sfrp1-deficient cancer tissues showed decreased expression of CSC markers in CCs." (PMID 38625488, 2024). "SFRP1 is overexpressed in cancer-associated fibroblasts (CAFs) compared to normal fibroblasts." (PMID 36968194, 2023). "Epigenetic repression of SFRP1 may cause dysregulation of cell proliferation, cell cycle, migration, and differentiation, which result in cancer cell formation and poor prognosis, and drug-treated resistance." (PMID 34336665, 2021). "Epigenetic silencing of SFRP1 may cause dysregulation of cell proliferation, migration, and invasion, which lead to cancer cells formation, disease progression, poor prognosis, and treatment resistance." (PMID 32074995, 2020). "The role of SFRP1 mutation in cancer-associated senescence warrants further research." (PMID 32074995, 2020). "To our knowledge, we show for the first time that low SFRP1 expression correlated significantly with a worse classification in the PRETEXT stratification system and to β-catenin mutations, indicating that SFRP1 gene silencing in β-catenin mutant cancer leads to a more aggressive cancer growth." (PMID 32189106, 2020). "Wnt signal pathway is activated in cancers by loss of SFRP1 expression." (PMID 30936781, 2019).